IL2 (interleukin 2)
Diseases named in the same sentence as IL2 in open-access papers (continued):
Sharing a sentence is not in itself a finding about the gene and the disease.
metastatic melanoma (continued). "Median overall survival for the clinical benefit group from the initiation of IL-2 to death or last follow-up was 61 months versus 17 months for the no clinical benefit group (p < 0.001) for metastatic melanoma." (PMID 25815245, 2015). "Further research is needed to understand how IL-2 produces a complete and durable response in a small group of patients with metastatic melanoma and renal cell carcinoma and fails to stop even disease progression in others." (PMID 26557408, 2015). "The resurgence of interest in immunotherapeutic methods (e.g. IL-2, CTLA4, PD-1, PDL-1) for the treatment of metastatic melanoma and cancer in general, opens new approaches to therapeutic design through the better understanding of modulation of the immune system." (PMID 27437102, 2014). "Interleukin-2 (IL-2), a protein produced primarily by CD4+ T-cells that activates and induces proliferation of natural killer (NK) cells, CD8+, and CD4+ T cells, is FDA-approved for the treatment of metastatic melanoma." (PMID 24743024, 2014). "This fact could be mainly explained by the modest results obtained with dacarbazine (DITC) and high-dose interleukin 2 (HD IL-2), the two unique FDA-approved therapies for metastatic melanoma until 2011." (PMID 23533766, 2013). "Until 2011, only two FDA therapies for metastatic melanoma were approved, dacarbazine and high dose interleukin 2 (HD IL-2), both of which do not increase median OS." (PMID 22385436, 2012). "The purpose of this study is to determine the toxicity and efficacy of temozolomide (TMZ) p.o. followed by subcutaneous (s.c.)low-dose interleukin-2 (IL2), granulocyte–monocyte colony stimulating factor (GM-CSF) and interferon-α 2b (IFNα) in patients with metastatic melanoma." (PMID 12610499, 2003). "In the present prospective randomized trial we reported the results of 124 patients with progressive metastatic melanoma who received a combined chemoimmunotherapy (IFN-, IL-2 combined with DTIC, cisplatin, BCNU, and tamoxifen) or a chemotherapy (DTIC, cisplatin, BCNU, and tamoxifen) alone." (PMID 11870502, 2002). "Based on successful preclinical results with IL-2 therapy in cancer models, high-dose IL-2 (aldesleukin; trade name Proleukin) was the first FDA-approved cancer immunotherapeutic drug for treating metastatic RCC in 1992 and metastatic melanoma in 1998, with substantial antitumor efficacy." (PMID 39218982, 2024). "In the phase 2 clinical trial, patients with unresectable or metastatic melanoma that was stage IIIC or IV who had confirmed radiologic progression and who had been previously treated with checkpoint inhibitor(s) and BRAF ± MEK targeted agents received lifileucel with IL-2." (PMID 36768737, 2023). "For instance, a preliminary report in 20 patients with metastatic melanoma treated with TIL therapy and IL-2 after a single intravenous dose of cyclophosphamide as lymphodepletion resulted in response rates of 60% in IL-2 naïve patients and 40% in patients with prior IL-2 exposure." (PMID 35538491, 2022). "Two pro-inflammatory cytokines, IL-2 and IFN-γ, showed some therapeutic benefit and were approved by the Food and Drug Administration (FDA) to treat a variety of cancers, including non-Hodgkin lymphoma, hairy cell leukemia, renal cell carcinoma, metastatic melanoma, and Kaposi’s sarcoma." (PMID 35159388, 2022). "In addition, a nonrandomized phase I trial was recently completed where patients with metastatic melanoma and ovarian cancer were treated in order to examine safety and efficacy of TIL-based ACT with low doses of IL-2 (ClinicalTrials.gov Identifier: NCT03158935)." (PMID 34066067, 2021).
metastatic melanoma (continued). "In addition, studies have evaluated the use of immunotherapy based on interferon alfa-2b and high-dose IL-2 to treat metastatic melanoma; however, the results were not as effective as in theory." (PMID 34675134, 2021). "The phase-I/II trials with NKTR-214, a pegylated interleukin-2 (IL-2) showing an enhanced response rate on top of nivolumab in several solid tumor types with expanded TILs, have attracted much attention and many doubts, while the phase-III trial is ongoing with metastatic melanoma." (PMID 30678257, 2019). "Supportive of this finding, administration of high-dose IL-2 (often utilized in conjunction with TIL therapy) can result in expansion of immunosuppressive ICOS+ Treg cells, which may be predictive of clinical outcomes in patients with metastatic melanoma." (PMID 31058083, 2019). "For example, high-dose (HD) IL-2 cancer immunotherapy stimulates the proliferation of cytotoxic CD8+ T-cells and NK cells, promoting tumor regression, and it has been approved for the treatment of metastatic melanoma and renal cancer for its anti-tumor activity." (PMID 29295974, 2018). "However, for advanced metastatic melanoma, only modest results are obtained with DTIC (1975), recombinant interferon α-2b (1995), and high-dose interleukin 2 (HD IL-2) (1998), the only three conventional therapeutic agents approved by the Food and Drug Administration (FDA) for metastatic melanoma." (PMID 28303522, 2017). "A recent publication from the NIH using TILs genetically engineered with an inducible IL-12 for metastatic melanoma shows the utility of IL-12 in solid tumors allowing for the absence of IL-2 administration and lower cell doses than trials using conventional TILs." (PMID 25890361, 2015). "Several agents, including interferon-alpha, high-dose interleukin-2 (IL-2), and checkpoint inhibitors targeting the cytotoxic T lymphocyte antigen 4 (CTLA-4) and programmed cell death 1 (PD-1) receptors have been approved by the FDA for the treatment of metastatic melanoma." (PMID 25992289, 2015). "Since cytokines in chemotherapies also alter the toxicity profile, future clinical trials might focus on new combinations, different dosages and dose distribution regimens of IL-2 and INF- to increase both efficacy and tolerability for patients with metastatic melanoma." (PMID 11870502, 2002). "Twelve metastatic melanoma patients were treated with non-myeloablative lymphodepleting chemotherapy, TIL, and low-dose subcutaneous IL-2 (125,000 IU/kg/day, maximum 9–10 doses over 2 weeks)." (PMID 30747243, 2019). "The addition of IL-2 and IFN-α to standard chemotherapy showed no beneficial effect on the survival rate, though it did improve the response rate in patients with metastatic melanoma." (PMID 31731818, 2019). "Unfortunately FDA-approved chemotherapy and immunotherapy used against advanced metastatic melanoma such as dacarbazine (DTIC), interferon (IFN) and interleukin-2 (IL-2) do not significantly improve patient outcomes in the majority (>80%) of patients." (PMID 20529378, 2010). "In summary, this prospectively randomized clinical trial showed no statistically significant benefit of IL-2, INF- based combined chemoimmunotherapy in patients with metastatic melanoma compared to chemotherapy alone." (PMID 11870502, 2002). "The addition of subcutaneous IL-2 and IFNalpha to BCDT chemotherapy in a randomized phase II trial resulted in immune activation but did not improve response rates in patients with metastatic melanoma, and indeed may increase some treatment-related toxicity." (PMID 9579834, 1998). "Recent studies have reported high clinical response rates in metastatic melanoma patients with TIL-based protocols in combination with non-myeloablative lymphodepleting chemotherapy (cyclophosphamide and fludarabine) immediately prior or added to infusion of TIL and high-dose IL-2 therapy." (PMID 23189169, 2012).
metastatic melanoma (continued). "Finally, a recent report in patients with metastatic melanoma and renal cell carcinoma treated with SBRT given in one, two, or three doses of 20 Gy, in combination with high dose IL-2 showed a response rate in non-irradiated lesions (abscopal responses) higher than expected with IL-2 alone." (PMID 23112958, 2012). "For instance, high clinical response rates have been obtained in metastatic melanoma patients with TIL-based protocols in combination with non-myeloablative lymphodepleting chemotherapy (cyclophosphamide and fludarabine) immediately prior or added to infusion of TIL and high-dose IL-2 therapy." (PMID 23189169, 2012).
autoimmune disease (355 papers, 2005 to 2026). A disorder resulting from loss of function or tissue destruction of an organ or multiple organs, arising from humoral or cellular immune responses of the individual to their own tissue constituents. "For example, overdoses of interleukin-2 (IL-2), proposed as an immunostimulatory adjuvant, have been associated with the development of autoimmune diseases." (PMID 40430917, 2025). "Genome-wide association studies established a possible role of the IL21/IL2 region in the human autoimmune diseases RA, SLE, type 1 DM, and SS." (PMID 39746095, 2025). "IL2 has been implicated in the regulatory pathways of autoimmune diseases, including signaling and promotion of the growth and proliferation of T cells; therefore, this protein plays an important role in generating immune responses." (PMID 38659590, 2024). "(A) The combination of evolutionary conservation (blue), open chromatin (red), and autoimmune disease-associated SNPs at the IL2 locus identify putative cRE in quiescent vs. 8 hr activated naïve CD4+ T cells." (PMID 39302339, 2024). "We know from the pathogenesis of autoimmune diseases that when a relative IL-2 deficiency develops, concomitant homeostatic disturbance and chronic inflammation improve with IL-2 replacement." (PMID 38549611, 2024). "The gene encoding IL-2, which is located on chromosome 4q27, has been found to house polymorphisms that are associated with various autoimmune diseases, including SLE, Ps, RA, ulcerative colitis, diabetes, and asthma." (PMID 39124628, 2024). "Mice with deficiencies in either IL-2 or its receptor display enlarged peripheral lymphoid organs, impaired activation-induced cell death, and autoimmune disorders, all attributed to a diminished Treg generation." (PMID 39000278, 2024). "Although several different mechanisms leading to Treg dysfunction have been reported, IL-2 and its signaling components are commonly associated with defective Treg function in autoimmune diseases." (PMID 36399073, 2023). "Lymphocytes T and B are activated following BNT162b2 administration, and IL-2, IL-4, IL-17, and IL-21 are associated with autoimmune diseases, especially in genetically susceptible individuals." (PMID 37238357, 2023). "This study aimed to identify an aptamer against mouse interleukin-2 (mIL-2) as one of the most important cytokines in autoimmune diseases for diagnostic and therapeutic purposes." (PMID 35756119, 2022). "As a result of this defect in GRAIL expression, the Tregs of patients with autoimmune diseases and allergic asthma degrade IL-2R-associated pJAK1 following activation with low dose IL-2, and thus cannot maintain pSTAT5 expression." (PMID 36569931, 2022). "Although single‐nucleotide polymorphisms in IL‐2 region are associated to a number of autoimmune diseases, further research is warranted to assess the association between IL‐2 gene polymorphisms and the risk of non‐response to hepatitis B vaccination." (PMID 33966331, 2021). "A role for IL-2 in immune regulation indicated why defects in IL-2, or in genes that contribute to IL-2 signalling, are associated with autoimmune diseases, including T1D." (PMID 35156097, 2021). "The decreases of total thymic MAIT cells were associated with decreases of total thymic cellularity because IL-2/IL-15Rβ deficiency causes severe autoimmune diseases due to impaired regulatory T cells." (PMID 33795689, 2021). "Taken together with the observance of raised anti-IL-2 antibodies in RA patients, loss of tolerance to IL-2 has been implicated as a mechanism through which autoimmune diseases are triggered due to its critical role in maintaining proper Treg function." (PMID 35008717, 2021). "Several studies have demonstrated that low-dose IL-2 therapy can successfully overcome Treg cell deficiency and increase the ratio of Treg to effector T cells in patients with RA and other autoimmune diseases." (PMID 33916798, 2021).
autoimmune disease (continued). "In vivo administration of blocking monoclonal antibodies to IL-2 diminishes the total number of Treg cells by depleting IL-2 bioactivity, causing autoimmune diseases." (PMID 34869064, 2021). "Peripheral Foxp3+ Treg survival and proliferation strictly depend on IL-2 and absence of IL-2 signaling in mice causes autoimmune disorders." (PMID 33496881, 2021). "A previous study also demonstrated that STAT5-deficient mice suffered from autoimmune diseases, which emphasized the role of IL-2 in regulatory T cell induction." (PMID 33584704, 2020). "The high levels of IL2RA in activated circulating immune cells and Tregs is exploited for IL-2 immunotherapy of tumors and autoimmune diseases; and certain polymorphisms of IL2RA are related to the risk of kidney cancer." (PMID 32983989, 2020). "IL-2, IL-2Rα, and IL-2Rβ deficient mice all die from severe lymphoproliferation and autoimmune disease in early life." (PMID 32676072, 2020). "Mice deficient in IL-2 (IL-2-KO) or its receptor (IL-2Rα-KO or IL-2Rβ-KO) develop spontaneous, multi-organ autoimmune disease, including autoimmune hemolytic anemia (AIHA), bone marrow (BM) failure (BMF), inflammatory bowel disease, and dacryoadenitis." (PMID 33319815, 2020). "SLE shares a significant overlap with the genetic susceptibility to type 1 diabetes (T1D), another autoimmune disease in which IL-2 signaling defects play a central role in disease etiology." (PMID 31781109, 2019). "The interleukin-2 (IL-2) receptor signaling pathway has been strongly implicated in type 1 diabetes (T1D) susceptibility and also in other autoimmune diseases." (PMID 31824482, 2019). "CD8 T cells can be found within the GC of several murine models of spontaneous autoimmune disease including in IL-2-deficient and scurfy mutant autoimmune disease." (PMID 31275308, 2019). "Treg deficiencies in autoimmune disorders have been variously ascribed to a decrease in IL-2 production or a decrease in response to IL-2 leading to a diminution in Treg numbers and/or a reduction of Treg functional activity." (PMID 30446251, 2018). "Recent reports on the loss of self-tolerance to IL-2 in autoimmune diseases encouraged us to evaluate the presence of anti-IL-2 Abs in Sardinian RA patients in association to antigens most frequently described as possible contributors to RA progression." (PMID 29379122, 2018). "Studies have shown that mice deficient in interleukin-2 are very likely to develop autoimmune diseases, for example, inflammatory bowel disease." (PMID 27594888, 2016). "Recent studies have linked defects in Tregs found both in mouse and human autoimmune disorders to reduced availability of IL-2." (PMID 25145773, 2015). "It will be important to determine if the variants mapping to the IL2-IL21 region that influence susceptibility to type 1 diabetes and other autoimmune diseases directly influence IL-2 or IL-21 production in a cell-intrinsic manner." (PMID 25652388, 2015). "Genetic susceptibility to several common autoimmune diseases maps to the IL-2RA gene region as well as other genes involved in IL-2 signaling and Treg function." (PMID 25457307, 2015). "The role of IL-2 in maintenance of self-tolerance is clear from studies of IL-2 or IL-2R-deficient mice that developed severe multi-organ autoimmune disease and early death." (PMID 26834735, 2015). "Previously, we reported various polymorphisms of IL2 gene and other genes which are involved in immune system in autoimmune diseases." (PMID 24959373, 2014). "Polymorphic variants at the interleukin-2 (IL2) locus affect the risk of several autoimmune disorders." (PMID 24154763, 2013). "Genes such as IL2 are located inthis region which is believed to be strongly associatedto autoimmune diseases etiology." (PMID 23862113, 2013). "In their study increased CSFT were associated with increased IL-2 production, division and ability to cause autoimmune disease following adoptive transfer." (PMID 24236211, 2013).